CCNB1 (cyclin B1)
Diseases named in the same sentence as CCNB1 in open-access papers (continued):
Sharing a sentence is not in itself a finding about the gene and the disease.
tumor (continued). "Interestingly, the reduction of cyclin B1 in MCF-7 cells impaired colony-forming ability, a hallmark of malignancy in tumor cells." (PMID 19113992, 2008). "Conversely, downregulation of cyclin B1, consequently reducing the activity of Cdk1/cyclin B1, could block the aggressive proliferation of tumor cells." (PMID 19113992, 2008). "Moreover, while control HeLa cells were progressively growing, the tumor growth of HeLa cells treated with siRNA targeting cyclin B1 prior to inoculation was strongly inhibited in nude mice, indicating cyclin B1 is indispensable for tumor growth in vivo." (PMID 19113992, 2008). "Elevated Cyclin B1 levels often precede the onset of tumor cell immortalization and aneuploidy." (PMID 18560566, 2008). "Furthermore, while control HeLa cells were progressively growing, the tumor growth of HeLa cells treated with cyclin B1 siRNA prior to inoculation was strongly inhibited in nude mice, indicating cyclin B1 is indispensable for tumor growth in vivo." (PMID 19113992, 2008). "We also noted that CDDP-treatment of pxn100 tumours induced the expression by >2.5-fold of genes encoding proteins that regulate the G2M cell cycle checkpoint (WEE1, CCNB1, CDC25C) and a gene encoding a protein involved in the anaphase promoting complex in mitosis (CDC6)." (PMID 15452549, 2004). "However, in the presence of circ‐Ccnb1, the interaction between Ccnb1 and Cdk1 was dissociated, accompanied by the formation of a large complex containing circ‐Ccnb1, Ccnb1 and Cdk1, resulting in inhibited Ccnb1 function as well as suppression of tumour growth." (PMID 41284375, 2025). "Moreover, miR-548b, when upregulated, could target CCNB1 (G2/mitotic-specific cyclin-B1), contributing to cell cycle regulation and reversing the tumor phenotype." (PMID 40283927, 2025). "The ‘tumor cells 1’ cluster had the gene expression characteristic of stem-like tumor cells with an elevated expression of genes involved in cell division and chromosome segregation such as Top2a, Mki67, Cenpf, Cenpe, Incenp, Anln, Ccna2, Kif20b, Ccnb1, and Smc4." (PMID 39769061, 2024). "Therefore, we hypothesize that CaSR may affect the cisplatin resistance of tumor cells through its effects on cyclin B1 and BRCA1." (PMID 39113697, 2024). "As a cell cycle regulator, CCNB1 may promote tumor cell proliferation via DNA hypomethylation." (PMID 38581717, 2024). "In vivo, we found that acacetin dramatically suppressed A549-xenografted tumor formation in nude mice, and inhibited the expression levels of cyclin B1 and cyclin D. As cyclin D is a key regulator of G1/S phase transmission, a decrease of this protein may be related to the G1/S arrest." (PMID 38287075, 2024). "In addition, CCNB1 can be directly targeted by microRNA-718, suppressing tumor immigration NSCLC." (PMID 37325647, 2023). "Interestingly, a single miR can play different roles in several tumor subtypes: miR-410-3p, for example, positively influencing proliferation and invasiveness in gonadotroph and corticotroph cells, increasing cyclin B1 levels, and activating MAPK, PTEN/AKT, and STAT3 signaling pathways." (PMID 37958702, 2023). "Similarly, intraperitoneal injection of kaempferol in BC mice contributes to the reduced tumor weight, increased apoptotic cells, and decreased levels of growth related markers, including c-Fos, c-Met, and cyclin B1 in tumor tissues, thus hampering tumor development." (PMID 37875863, 2023). "In addition, CDK1, CDC20, CCNA2, CCNB1 and CCNB2 expressions may be involved in the regulation of monocytes and tumor-associated macrophages (TAMs) in HCC, respectively." (PMID 36605491, 2023). "Additionally, for the ceRNA crosstalk pair MAPK1–CCNNB1, studies found that EGF-induced activation of ERK (MAPK1) could promote β-catenin (CCNB1) transactivation and tumor cell invasion." (PMID 35433687, 2022).
tumor (continued). "This proposed axis of SIRT4-dependent inhibition of survivin and retention of cytoplasmic cyclin B1 in the suppression of tumor cell cycle progression and induction of apoptosis could shed light on the development of therapeutic targets against HCC tumorigenesis." (PMID 33931611, 2021). "Therefore, its down-regulation—consequently reducing the activity of Cdk1/Cyclin B1—could block the aggressive proliferation of tumor cells." (PMID 34944868, 2021). "Results showed that um-PEA inhibited tumor cell proliferation via peroxisome proliferator-activated receptor α and G protein-coupled receptor 55, induced cell cycle arrest in the G2/M phase, possibly through cyclin B1/CDK1 upregulation, and induced DNA fragmentation." (PMID 33923494, 2021). "The same microRNAs may even play different roles in different tumor subtypes: miR-410-3p significantly upregulates proliferation, invasiveness, cyclin B1 levels and activation of MAPK, PTEN/AKT, and STAT3 signaling pathways in gonadotroph and corticotroph cells but not in somatotroph cells." (PMID 32201880, 2020). "Furthermore, immunoblotting assay also showed that the protein levels of MELK, phospho-FOXM1 (T600), and its downstream targets (PLK1, Cyclin B1 and Aurora B) were much higher in tumor cell lysates derived from MELK-overexpressing mice than those from the control group." (PMID 32047721, 2020). "Thus, BITC reduced cyclin B1 and Cdk1 levels, inducing apoptosis to suppress tumor growth." (PMID 33263014, 2020). "Thus, miR-9 is a tumor-suppressive microRNA that may inhibit the IGF1R pathway to regulate the targeting of cyclin B1 and N-cadherin, and increase E-cadherin in CRC cells in HG-concentration medium." (PMID 30965609, 2019). "Moreover, miR-144 negatively regulates CCNB1 to delay tumor formation." (PMID 31007608, 2019). "Interestingly, studies also revealed that abnormally expressed cyclin B1 could be discerned by the immune system as tumor antigens in early stages of cancer, which is possible to be used for early cancer detection by monitoring the immune responses." (PMID 27903976, 2017). "Moreover, we also confirmed the effect of Cyclin B1 on E-cadherin in vivo mice tumor model." (PMID 25962181, 2015). "Therefore potential introduction of miR-379 could be used as a therapeutic intervention to regulate the expression of Cyclin B1 and further control tumour cell proliferation." (PMID 23874748, 2013). "This discrepancy might be due to dissimilar expression of cyclin B1 in different tumor types." (PMID 22682366, 2012). "Moreover, that the level of cyclin B1 was lower in L50 tumours suggests that they might be less aggressive and, possibly, more responsive to chemotherapy, a hypothesis that we plan to test in the future." (PMID 22107808, 2011). "Furthermore high cyclin B1 expression was significantly more common among triple-negative tumours." (PMID 19293801, 2009). "Furthermore, USP39 knockdown resulted in the inhibition of tumor growth in xenografts in nude mice, accompanied by a reduction in the expression levels of forkhead box protein M1 (FoxM1) and its target genes polo-like kinase 1, cyclin B1, and centromere protein A." (PMID 40990019, 2025).
tumor (continued). "A study based on microarray data identified five genes (CDK1, CDC20, CCNB1, CENPF, and MAD2L1) related to the tumor stage, early diagnosis, and poor outcomes." (PMID 40282296, 2025). "By IHC staining, we found that STOX1‐A, cyclin B1, and p‐AKT1 (Ser473) were all predominantly expressed in the nucleus of tumor cells." (PMID 40567110, 2025). "The mitochondrial relocation of CCNB1/CDK1 enhances the ATP production needed for DNA damage repair, aiding cell survival and contributing to tumor resistance to DNA-damaging treatments such as chemotherapy and radiotherapy." (PMID 40675964, 2025). "A heatmap of the 11 mRNA expression levels of the tumor samples displayed that the seven genes, including CCNB1, CCNB2, CHEK1, FEN1, PTTG1, RACGAP1, and UBE2C, had higher expression levels in the tumor tissue." (PMID 41009526, 2025). "Since STAT3 activation is sustained by IL-6 signaling, CCNB1 likely contributes to a positive feedback loop between IL-6 and JAK-STAT3, further reinforcing tumor immune evasion." (PMID 40430484, 2025). "Protein expressions of p‐CDC2, cyclin B1 and URB1 in tumor samples were also evaluated in vivo, and the findings aligned with the in vitro results." (PMID 39673181, 2025). "Our examinations showed a significant overexpression of five genes (CCNB1, CCNB2, PTTG1, RACGAP1, and UBE2C) in the tumor samples." (PMID 41009526, 2025). "This study found that in cancer types with over 12 tumor and para-cancer tissues, the genes RRM2, TK1, CCNB1, DLGAP5, CCNA2, MYBL2, and HJURP were repeatedly overexpressed across various cancer tissues." (PMID 39669580, 2024). "FT282-C11 cells have low expression of FOXM1, FOXM1-P (activated FOXM1), CCNB1 (canonical FOXM1 target), FOXA1, and FOXK2 (all oncoproteins), and elevated FOXO3a (a tumor suppressor), as compared to HGSOC cells, validating their utility as a normal control." (PMID 38704607, 2024). "Survival data were used to compare various patient subgroups, including tumor stage (pTa, pT1, and pT2), grade (LG and HG), and gene expression levels of CDC20 and CCNB1, with respect to overall survival." (PMID 39795587, 2024). "According to human data derived from the TCGA and GTEx databases, decreased expressions of miR-4516 and increased expressions of Wnt 8B, DVL3, FOSL1, CCNA1, CCNB1, CDK1, and CDK2 in tumor tissue contributed to the progression of LUAD." (PMID 38930863, 2024). "Functional assays demonstrated that two miRNAs acted as tumor-suppressive miRNAs in BC cells by targeting cell-cycle-related genes (e.g., TRIP13, CCNB1, RAD51, PSPH, CENPN, KPNA2, and MXRA5)." (PMID 39728605, 2024). "We found that the down-regulated miR-5100 target genes (PLK1, CCNB1, CDKN2A) were significantly upregulated, indicating their tumor-promoting effect in PCa." (PMID 39590378, 2024). "CircRNA circ-Ccnb1, derived from the cell proliferation-related gene Ccnb1, can form a triplet complex with Ccnb1 and CDK1, block the function of Ccnb1 and CDK1, and inhibit the activities of tumor cells." (PMID 39199340, 2024). "HMGB2 in POSTN+ fibroblasts is predicted to bind to PLD2, LRP5, MYLK, and CD44 on tumor cells, regulating downstream genes, including BIRC5, CCNA2, CCNB1, CCNB2, CDC20, and MKI67, which are related to the cell cycle." (PMID 38519500, 2024). "Suppressed cellular proliferation.Promoted cell cycle arrest in G2 Phase by ↑ p21 expression and ↓ cdc2 and cyclin B1.Induced apoptosis by ↓ Bid expression and activated PARP cleavage.Inhibited tumor growth in vivo." (PMID 37836809, 2023).
tumor (continued). "The result also showed that CDK1, CDK5, CDC20, CCNA2, CCNB1 and CCNB2 mRNA expression levels within tumor tissues were significantly increased compared with the adjacent normal tissues." (PMID 36605491, 2023). "Many researchers have identified CDCA8 as a novel oncogene, which predicts a poor prognosis in HCC as well as promotes tumor proliferation via MEK/ERK, AKT/β-Catenin, and CDK1/cyclin B1 signaling." (PMID 37854038, 2023). "Significant CCNB1 overexpression was observed in LAC patients and was correlated with tumor stage and shorter OS." (PMID 36973678, 2023). "In tumor migration, hnRNPR directly interacts with CCNB1 and CENPF mRNA to contribute to tumor malignancy and poor outcomes in cancer patients." (PMID 37479693, 2023). "The results revealed that AURKA, BIRC5, CCNB1, CDK1, CDKN3 and TYMS were significantly upregulated in tumor tissues." (PMID 37393234, 2023). "The CDK1, CDK5, CDC20, CCNA2, CCNB1 and CCNB2 expression levels (tumor sample: n = 369 vs. normal sample: n = 160) were upregulated in HCC group compared with the non-carcinoma group (Analysis by GEPIA dataset)." (PMID 36605491, 2023). "The main lymphocyte subgroups involved in anti-tumor immunity, including CD4 + Tcm, CD4 + Tem, and CD8 + T cells, showed a significant increase in the CCNB1 low expression group." (PMID 37592341, 2023). "The immunohistochemistry result of subcutaneous tumor indicated that knockdown CLSPN significantly down regulated CCNA2, CCNB1, CDK1, CDK2 and Ki67 expression." (PMID 37268895, 2023). "Next, we confirmed the positive linear correlations between the mRNA expression of MKI67 vs. CCNA2, CCNB1, CCNB2, and CCNE2, suggesting their role in tumor progression." (PMID 36151566, 2022). "Given the functional mechanism and carcinogenic potential of CCNB1, CDK1, and PAICS miRNAs, these three genes' upstream miRNAs ought to be tumor suppressive." (PMID 36081668, 2022). "The role of hsa-miR-508-5p upstream of IGF1, CHEK1 and CCNB1 in IDD remains to be explored, but it has been extensively studied in various tumour tissues and cardiovascular." (PMID 36175893, 2022). "Tumour CCNB1 mRNA levels were also positively correlated with those of CCNE1 and were particularly high in tumours with CCNE1 amplification, suggesting that this relationship was also relevant to tumours." (PMID 35444283, 2022). "The correlation between the expression of cell cycle-related genes and immune cells suggested roles for CDK4, CCNB1, CHEK1 and CDKN2A in regulating HCC tumor immunology." (PMID 36403263, 2022). "The expression of MKI67, MYBL2 and CCNB1 was significantly correlated with miR-200c-3p expression, both in pre- and post-NCT tumor samples." (PMID 35625994, 2022). "Eight hub genes (CDK1, EGFR, UBC, MYC, CCNB1, RHOB, CDC6, and CDC20) have tumor suppressor functions, while five hub genes (CDK1, EGFR, FYN, UBC, and CCNB1) are protein kinases as well." (PMID 35632527, 2022). "Then Western blotting was used to test the protein expression levels of FOXM1, Cyclin B1 and CENPF in tumour tissues, the results showed that the protein expression were inhibited by SH3PXD2A-AS1 knockdown." (PMID 35410446, 2022). "To validate expression levels of the CCNB1/CDC42/MAPK7/CD44 gene signatures in GBM, we explored the HPA database for IHC to compare gene expression levels between GBM tumor tissues and normal samples." (PMID 35008426, 2022). "CCNB1 and CCNA2 are up-regulated in a variety of tumors and promote tumor proliferation, and also have a prognostic role." (PMID 35816352, 2022). "We identified significantly increased mRNA levels of the CCNB1/CDC42/MAPK7/CD44 oncogenes in pan cancers, including GBM tumor tissues compared to normal tissues from TCGA, using the TIMER bioinformatics tool." (PMID 35008426, 2022). "SELICICLIB and KENPAULLONE, matched by CCNB1, can selectively inhibit CDK activity and block DNA replication in tumor cells by influencing the cell cycle." (PMID 35370655, 2022).
tumor (continued). "A bioinformatics analysis through TIMER online web tool with default settings showed significantly increased messenger (m)RNA levels of CCNB1/CDC42/MAPK7/CD44 in pan cancers, including GBM tumor tissues compared to normal tissues from TCGA)." (PMID 35008426, 2022). "Knockdown of RAD6A suppressed tumor growth and decreased the level of H2B, as data demonstrated positive correlation between RAD6A and CCNB1 in ESCC tissues." (PMID 35321657, 2022). "The results of immunohistochemistry showed that protein expression levels of AURKA, CCNB1, DLGAP5, and NCAPG were upregulated in tumor tissue compared with normal tissue." (PMID 36250027, 2022). "Western blot analyses further indicated that treatment with 75 mg/kg ribociclib alone only partially suppress cell cycle proteins such as Cdc25C, cyclin B1 and p‐Cdc2 in HCC21‐0208 tumour." (PMID 33179425, 2021). "Meanwhile, the expression of cell cycle-related genes such as E2F1, Cyclin D1, Cyclin B1, and CDK2 was also decreased after ITPR3 knockdown while P21, as a classical tumor suppressor gene was upregulated." (PMID 33573671, 2021). "Both drugs inhibited tumour growth and reduced tumour weight, but only 5MeOIndox reduced CDK1/cyclin B1 complex levels." (PMID 34503199, 2021). "Subsequently, we performed the mRNA and protein detection of proliferation markers (CYCLIN B1, PCNA, and KI-67) and apoptosis markers (BAX and BCL2) in the tumor tissues of each mice group." (PMID 34447747, 2021). "For instance, overexpression of CCNB1 and CDK1 induces tumor growth and metastasis in human breast cancer." (PMID 33627711, 2021). "The difference in expression comparing tumor and normal tissues were found to be significant in eight genes (PLAU, EGR1, IL6, EGFR, EZH2, BMP4, CCNB1, NMI)." (PMID 34077304, 2021). "And the content of cell cycle-related proteins (CDK1, cyclin B1 and cyclinD1) in LINC01559-silenced H1299 cells was also significantly reduced, indicating that knockdown of LINC01559 blocked the cycle of tumor cells." (PMID 34823534, 2021). "Intriguingly, the expression levels of CCNB1, CDC20, and CENPE in PBMCs were completely opposite to those observed in tumor tissues." (PMID 34660300, 2021). "High expression of CCNB1 and CCNA2 significantly correlates with tumor relapse and predicts poorer prognosis in GC patients (P < 0.05)." (PMID 34126961, 2021). "By using TCGA and THPA databases, we found five genes, CDK1, CDC20, CCNB1, CENPF, and MAD2L1, that were related to the early diagnosis, tumour stage, and poor outcomes of HBV-HCC." (PMID 34603487, 2021). "And the heatmap of the enriched genes in the pathways indicated that key genes involving tumor proliferation such as BRCA1, CDK1, and CCNB1 et, al." (PMID 35095481, 2021). "For tumor stage, significant differences among stage 1, stage 2, and stage 3 were shown in NDC80, CCNB1, KIF20A, DTL, and TOP2A of the key genes from Jia Liver data set (P < 0.05)." (PMID 34746301, 2021). "In summary, we confirmed TTK, CCNB1 and CCNB2 were pro-oncogenes that mainly expressed in tumor cells and immune cells." (PMID 32969465, 2020). "The levels of USP7 and mitotic markers, including AURKB, CCNB1, and PLK1, were higher in tumor samples than in normal tissues." (PMID 33207738, 2020). "Among the genes related to prognosis, the expression levels of CCNB1, NQO1, NUF2, and CHEK1 were high in tumor tissues (p < 0.05)." (PMID 33424998, 2020). "A study found that in renal cell carcinoma, the down-regulation of Aurora A kinase induces a decrease in the expression of cyclin B1/CDK1 complex, and inhibits cell proliferation and metastasis by blocking ERK activity, thereby exerting anti-tumor effects." (PMID 32518522, 2020). "The expression of Cyclin B1 and CDK1 was reduced in tumors from BITC-treated mice, which resulted in the suppression of tumor growth." (PMID 33263014, 2020).